SERPINB3 (serpin family B member 3)
Diseases named in the same sentence as SERPINB3 in open-access papers (continued):
Sharing a sentence is not in itself a finding about the gene and the disease.
renal disease (1 paper, 2018). "Particularly, SERPINB3-injected mice developed a milder and markedly delayed renal disease involvement." (PMID 30254646, 2018). "Interestingly, improvement in clinical and serological parameters occurred in NZB/W F1 mice both with the preventive and the therapeutic approach, suggesting a protective potential of SERPINB3 even when renal disease is already established." (PMID 30254646, 2018).
SERPINB3 also shares sentences with these, for which no sentence is quoted: adenocarcinoma (14 papers); cervical squamous cell carcinoma (11); esophageal cancer (6); esophageal squamous cell carcinoma (6); non-small cell lung carcinoma (6); head and neck cancer (5); liver cirrhosis (3); oesophageal cancer (3); ovarian cancer (3); pneumonia (3); prostate carcinoma (3); squamous cell lung carcinoma (3); bacterial infection (2); COVID-19 (2); dysplasia (2); head and neck squamous cell carcinoma (2); idiopathic pulmonary fibrosis (2); liver (2); malignant neoplasms of the skin (2); oral squamous cell carcinoma (2); osteosarcoma (2); small cell carcinoma (2); small cell lung carcinoma (2); Ulcer (2); acute coronary syndrome (1); acute monocytic leukemia (1); adenosquamous carcinoma (1); amoebiasis (1); anemia (1); atherosclerosis (1).
A further 58 diseases each share a sentence with SERPINB3 in 1 paper.